IKBKB (inhibitor of nuclear factor kappa B kinase subunit beta)
Description:
Serine kinase that plays an essential role in the NF-kappa-B signaling pathway which is activated by multiple stimuli such as inflammatory cytokines, bacterial or viral products, DNA damages or other cellular stresses. Acts as a part of the canonical IKK complex in the conventional pathway of NF-kappa-B activation. Phosphorylates inhibitors of NF-kappa-B on 2 critical serine residues. These modifications allow polyubiquitination of the inhibitors and subsequent degradation by the proteasome. In turn, free NF-kappa-B is translocated into the nucleus and activates the transcription of hundreds of genes involved in immune response, growth control, or protection against apoptosis. In addition to the NF-kappa-B inhibitors, phosphorylates several other components of the signaling pathway including NEMO/IKBKG, NF-kappa-B subunits RELA and NFKB1, as well as IKK-related kinases TBK1 and IKBKE. IKK-related kinase phosphorylations may prevent the overproduction of inflammatory mediators since they exert a negative regulation on canonical IKKs. Phosphorylates FOXO3, mediating the TNF-dependent inactivation of this pro-apoptotic transcription factor. Also phosphorylates other substrates including NAA10, NCOA3, BCL10 and IRS1. Phosphorylates RIPK1 at 'Ser-25' which represses its kinase activity and consequently prevents TNF-mediated RIPK1-dependent cell death (By similarity). Phosphorylates the C-terminus of IRF5, stimulating IRF5 homodimerization and translocation into the nucleus. Following bacterial lipopolysaccharide (LPS)-induced TLR4 endocytosis, phosphorylates STAT1 at 'Thr-749' which restricts interferon signaling and anti-inflammatory responses and promotes innate inflammatory responses. IKBKB-mediated phosphorylation of STAT1 at 'Thr-749' promotes binding of STAT1 to the ARID5A promoter, resulting in transcriptional activation of ARID5A and subsequent ARID5A-mediated stabilization of IL6. It also promotes binding of STAT1 to the IL12B promoter and activation of IL12B transcription.
Synonyms: IKK-beta; IKK-2; IKK2; NFKBIKB; IKKB; IMD15; IMD15A; IMD15B
Tractability: Small molecule: a drug acting on it is in phase 2 or 3 trials; a structure with a bound ligand is known; a high-quality ligand is known; it belongs to a druggable protein family. PROTAC: UniProt records ubiquitination sites on it; ubiquitination databases record sites on it; its protein half-life has been measured; a small molecule that binds it is known.
Target class: Enzyme; Kinase; Protein Kinase; Other protein kinase group
Chemical probes: ACHP, BI 605906 (high quality), BMS-066, CHEMBL520308, PD080754, PD081229, PD081396, PD081841, PD082311, PD082375, PD082422, PD082468, PD082532, PD083015, PD083068, PD083422, PD083427, PD083656, PD083790, PD084000, and 14 more
Safety:
Unwanted effects reported when the protein is acted on. In parentheses: how it was acted on, where the effect was seen, and who reports it.
skin rash (source: ClinPGx)
Gene: Protein-coding gene on chromosome 8 (42,271,302 to 42,332,460, forward strand). Ensembl gene ENSG00000104365.
Subcellular location: Cytoplasm; Nucleus; Membrane raft
Subcellular location (Human Protein Atlas): Cytosol
Pathways (Reactome):
Immune System: Activation of NF-kappaB in B cells; CLEC7A (Dectin-1) signaling; Downstream TCR signaling; ER-Phagosome pathway; FCERI mediated NF-kB activation; IKK complex recruitment mediated by RIP1; IRAK1 recruits IKK complex; IRAK1 recruits IKK complex upon TLR7/8 or 9 stimulation; Interleukin-1 signaling; MAP3K8 (TPL2)-dependent MAPK1/3 activation; Modulation of host responses by IFN-stimulated genes; NF-kB activation through FADD/RIP-1 pathway mediated by caspase-8 and -10; NOD1/2 Signaling Pathway; PKR-mediated signaling; RIP-mediated NFkB activation via ZBP1; Regulation of NF-kappa B signaling; SLC15A4:TASL-dependent IRF5 activation; TAK1-dependent IKK and NF-kappa-B activation; TICAM1, RIP1-mediated IKK complex recruitment; TRAF6 mediated NF-kB activation
Disease: IKBKB deficiency causes SCID; IKBKG deficiency causes anhidrotic ectodermal dysplasia with immunodeficiency (EDA-ID) (via TLR); IkBA variant leads to EDA-ID; SARS-CoV-2 activates/modulates innate and adaptive immune responses
Signal Transduction: NF-kB is activated and signals survival; Regulation of TNFR1 signaling; TNFR1-induced NF-kappa-B signaling pathway; p75NTR recruits signalling complexes
Cellular responses to stimuli: Turbulent (oscillatory, disturbed) flow shear stress activates signaling by PIEZO1 and integrins in endothelial cells
Gene Ontology:
Molecular function: identical protein binding; IkappaB kinase activity; protein binding; protein heterodimerization activity; protein homodimerization activity; protein kinase activity; protein kinase binding; protein serine kinase activity; protein serine/threonine kinase activity; scaffold protein binding; transferrin receptor binding; ATP binding
Biological process: canonical NF-kappaB signal transduction; cellular response to tumor necrosis factor; interleukin-1-mediated signaling pathway; negative regulation of bicellular tight junction assembly; negative regulation of cytokine production involved in inflammatory response; peptidyl-serine phosphorylation; positive regulation of canonical NF-kappaB signal transduction; positive regulation of DNA-templated transcription; positive regulation of transcription by RNA polymerase II; protein localization to plasma membrane; protein maturation; protein phosphorylation; regulation of establishment of endothelial barrier; tumor necrosis factor-mediated signaling pathway; antigen processing and presentation of exogenous peptide antigen via MHC class I, TAP-dependent; Fc-epsilon receptor signaling pathway; inflammatory response; innate immune response; MyD88-dependent toll-like receptor signaling pathway; regulation of toll-like receptor signaling pathway; regulation of tumor necrosis factor-mediated signaling pathway; response to virus; stimulatory C-type lectin receptor signaling pathway; stress-activated MAPK cascade; T cell receptor signaling pathway; and 3 more
Cellular component: cytoplasm; cytosol; IkappaB kinase complex; membrane raft; nucleus; CD40 receptor complex; cytoplasmic side of plasma membrane
Genetic constraint (gnomAD): Loss-of-function variants: 34 observed, 95.98 expected, observed/expected ratio (o/e) 0.35, 90% interval 0.27 to 0.47. The synonymous counts are far from expectation, so gnomAD's model fits this gene poorly and the ratio says little. Missense variants: 590 observed, 856.19 expected, observed/expected ratio (o/e) 0.69, 90% interval 0.64 to 0.74. Synonymous variants: 259 observed, 333.94 expected, observed/expected ratio (o/e) 0.78, 90% interval 0.7 to 0.86.
Gene-disease validity (ClinGen):
ClinGen rates the evidence that IKBKB causes each of these diseases.
severe combined immunodeficiency due to IKK2 deficiency (autosomal recessive): Definitive. Severe combined immunodeficiency due to IKK2 deficiency is a rare, genetic form of primary immunodeficiency characterized by life-threatening bacterial, fungal and viral infections with the onset in infancy, and failure to thrive.
immunodeficiency 15a (autosomal dominant): Moderate.
Cancer hallmarks: escaping immune response to cancer (suppresses); escaping programmed cell death (suppresses); tumour promoting inflammation (suppresses); escaping programmed cell death (promotes); proliferative signalling (promotes); invasion and metastasis (promotes); angiogenesis (promotes); tumour promoting inflammation (promotes)
Homologues: Orthologues: macaque IKBKB (99% identical), chimpanzee IKBKB (98% identical), rabbit IKBKB (95% identical), dog IKBKB (95% identical), pig IKBKB (94% identical), mouse Ikbkb (93% identical), guinea pig IKBKB (92% identical), rat Ikbkb (90% identical), tropical clawed frog ikbkb (70% identical), zebrafish ikbkb (60% identical), Drosophila melanogaster IKKbeta (25% identical). Paralogues in human: CHUK (50% identical), TBK1 (20% identical), IKBKE (19% identical).
Diseases named in the same sentence as IKBKB in open-access papers:
IKBKB is named in the same sentence as 305 diseases in open-access papers, as found by Europe PMC text mining. Sharing a sentence is not in itself a finding about the gene and the disease. The quoted sentences say what the papers report.
Insulin resistance (168 papers, 2008 to 2026). Increased resistance towards insulin, that is, diminished effectiveness of insulin in reducing blood glucose levels. "Activation of inhibitor of nuclear factor kappa-B kinase subunit beta causes both hepatic and systematic insulin resistance." (PMID 30513975, 2018). "Inhibition of IKBKB with salicylates or through targeted gene disruption causes a dramatic improvement of insulin sensitivity in animal models of insulin resistance such as ob/ob mice and obese Zucker fatty rats." (PMID 18570670, 2008). "Serine kinases, such as c-Jun-N-terminal Kinase (JNK) and inhibitor of nuclear factor kappa-B kinase subunit beta (IKKβ), contribute to insulin resistance through phosphorylation of IRS-1." (PMID 38257161, 2024). "Activation of inhibitor of nuclear factor kappa-B kinase subunit beta (IKK-β) is important for the improvement of insulin resistance in obesity." (PMID 30678306, 2019). "The pro-inflammatory tumor necrosis factor-α/inhibitor of nuclear factor kappa-B kinase subunit beta signaling pathway mediates insulin resistance." (PMID 30513975, 2018). "Insulin resistance has been linked to the presence of several pro-inflammatory cytokines, including IL-6, as well as SOCS, ER stress, and the inhibitor of nuclear factor kappa-B kinase subunit beta (IKKB) and c-Jun N-terminal kinase (JNK) signaling pathways." (PMID 38317257, 2024). "Finally, treatment with VSL#3 probiotics alleviated obesity, hepatic steatosis, and insulin resistance, as well as reduced inflammation, downregulating the activation of TNFα/inhibitor of nuclear factor kappa-B kinase subunit beta (IKK-β) signaling pathway in high-fat diet-fed mice." (PMID 36139402, 2022). "Mitochondrial dysfunction and consequent increases in ROS activate various serine kinases and inhibitor of nuclear factor kappa-B kinase subunit beta (IKKβ), which phosphorylates IRS proteins, leading to insulin resistance." (PMID 32987623, 2020). "In terms of insulin resistance, IL-1β interferes with insulin signaling by activating stress kinases like JNK and inhibitor of nuclear factor kappa B kinase subunit beta (IKKβ), which phosphorylate insulin receptor substrate proteins and disrupt downstream insulin signaling cascades." (PMID 38044678, 2024). "IKBKB was discovered to play a role in the development of T2DM, and studies have shown that its deletion inhibited the production of inflammatory cytokines that increase insulin resistance." (PMID 36360783, 2022).
Obesity (88 papers, 2009 to 2025). Accumulation of substantial excess body fat. "We hypothesized that polymorphisms in genes involved in the hypothalamic IKKβ/NF-κB signaling pathway (NFKB1, IKBKB, and SOCS3), alone or in interaction with nutrients, are associated with energy imbalance and obesity pathogenesis in humans." (PMID 30886629, 2019). "In this study, we investigated gene–gene and gene–environment interactions in the association between variants of three genes (NFKB1, IKBKB, SOCS3), macronutrient and alcohol intakes, and obesity-related phenotypes (BMI, alternative BMI cut-offs for East and South Asians, and waist circumference)." (PMID 30886629, 2019). "As for rs3747811 (IKBKB), it has not been yet investigated in previous studies for its involvement in the development of obesity-related phenotypes, and was only found to decrease the risk of colorectal cancer combined with rs4648110 (NFKB1)." (PMID 30886629, 2019). "However, this study is the first to investigate gene–gene and gene–environment interactions between polymorphism in NFKB1, IKBKB, SOCS3, macronutrient and alcohol intakes, in the association between overnutrition and obesity-related phenotypes in human subjects." (PMID 30886629, 2019). "IKBKB and IKBKG genes were upregulated in patients with normal weight compared to those who were of extreme weight (p = 0.0287; 0.0083, respectively) or extreme obesity (p = 0.0006 for IKBKG)." (PMID 39337357, 2024). "In addition, this study is one of the first to investigate gene–gene and gene–environment interactions between NFKB1, IKBKB, SOCS3 and macronutrient intakes on human and their effect on obesity-related phenotypes." (PMID 30886629, 2019).
breast carcinoma (77 papers, 2005 to 2025). "Previous studies have found an association between IKBKB and the prognosis of a variety of tumors, including osteosarcoma, gastric cancer, skin cancer, and breast cancer." (PMID 34109216, 2021). "Moreover, a significant inverse association was observed between miR-16 and IKBKB expression in breast cancer specimens." (PMID 26993770, 2016). "Furthermore, an inverse correlation between miR-16 and IKBKB expression was found in breast cancer tissues, miR-16 was negatively associated with T stages, whereas IKBKB was positively correlated with T, N and clinical stages." (PMID 26993770, 2016). "As miR-16 could directly target IKBKB in breast cancer cells, we wondered whether miR-16 expression was negatively associated with IKBKB expression in breast cancer tissues." (PMID 26993770, 2016). "Moreover, miR-16 was highly expressed in Taxol-sensitive breast cancer patients and negatively associated with T stages, whereas IKBKB was lowly expressed in Taxol-sensitive breast cancer and positively correlated with T, N and clinical stages." (PMID 26993770, 2016). "Collectively, our results showed that circRNA-14,052 promotes breast cancer progression via the miR-214-3p/IKBKB axis." (PMID 41044672, 2025). "In this study, we identified circRNA-14,052 as a novel oncogenic circRNA that promotes breast cancer progression by sponging miR-214-3p and upregulating IKBKB, thereby activating the IL-6/JAK2/STAT3 signaling axis." (PMID 41044672, 2025). "First, we investigated the role of the circRNA14052/miR-214-3p/IKBKB axis in only two breast cancer cell lines: MCF-7 (Luminal A cell line) and MDA-MB-231 (TNBC cell line)." (PMID 41044672, 2025). "Other research on IKBKB found that it can promote the growth of breast cancer cells, although this was only investigated at the protein level." (PMID 39337357, 2024). "Downregulation of IKBKB expression by MicroRNA-16 enhances the sensitivity of breast cancer cells to paclitaxel treatment." (PMID 38418940, 2024). "This, together with our demonstration of a negative correlation between gene expressions of E2F3, CDK2 and CCNA2 with IKBKB expression in breast cancer patients, implicates IKKβ in regulating cell cycle progression in cooperation with miR-125b." (PMID 38093346, 2023). "The results showed that some of the genes related to the prognosis of breast cancer (IKBKB, ATG16L2, CLN3, MBTPS2, TSC2, and CAPN10) had a higher frequency of mutations." (PMID 34457116, 2021). "The breast cancer MDA-MB-453 cell line with ectopic expression of IKBKB has a higher proliferation rate than its IKBKB-negative counterpart." (PMID 26993770, 2016). "Up-regulation of IKBKB suppressed Taxol-induced apoptosis and led to an increased resistance to Taxol, and restoring IKBKB expression in miR-16-overexpressing breast cancer cells recovered Taxol resistance." (PMID 26993770, 2016). "Taken together, our data demonstrates that miR-16 sensitizes breast cancer cells to Taxol through the suppression of IKBKB expression, and targeting miR-16/IKBKB axis will be a promising strategy for overcoming Taxol resistance in breast cancer." (PMID 26993770, 2016). "In this study, we found that circRNA-14,052 may promote breast cancer progression through the sponging of miR-214-3p, leading to subsequent dysregulation of the IKBKB pathway." (PMID 41044672, 2025). "Collectively, circRNA-14,052 knockdown could inhibit the breast cancer progression in vitro via miR-214-3p/IKBKB/IL-6/JAK2/STAT3 axis." (PMID 41044672, 2025). "In conclusion, we found that circRNA-14,052 could promote the progression of breast cancer via the miR-214-3p/IKBKB/IL6/JAK/STAT3 axis." (PMID 41044672, 2025). "Similarly, a recent study reported that circIKBKB is generated from the IKBKB gene, which codes NF-κB kinase subunit beta, facilitating cancer cell metastasis in breast cancer by activating NF-κB pathway." (PMID 35945200, 2022).